SOX30 (SRY-box transcription factor 30)
Description:
Acts both as a transcriptional activator and a repressor. Binds to the DNA sequence 5'-ACAAT-3' and shows a preference for guanine residues surrounding this core motif. Binds to its own promoter and activates its own transcription (By similarity). Required to activate the expression of postmeiotic genes involved in spermiogenesis (By similarity). Binds to the promoter region of CTNNB1 and represses its transcription which leads to inhibition of Wnt signaling. Also inhibits Wnt signaling by binding to the CTNNB1 protein, preventing interaction of CTNNB1 with TCF7L2/TCF4.
Tractability: No criterion of Open Targets' tractability assessment is met for any kind of drug.
Gene: Protein-coding gene on chromosome 5 (157,625,679 to 157,671,480, reverse strand). Ensembl gene ENSG00000039600.
Subcellular location: Nucleus; Cytoplasm
Subcellular location (Human Protein Atlas): Nucleoplasm; Vesicles; Cytosol
Gene Ontology:
Molecular function: beta-catenin binding; protein binding; RNA polymerase II cis-regulatory region sequence-specific DNA binding; sequence-specific double-stranded DNA binding; DNA-binding transcription activator activity, RNA polymerase II-specific; DNA-binding transcription factor activity, RNA polymerase II-specific; DNA-binding transcription repressor activity, RNA polymerase II-specific; DNA-binding transcription factor activity
Biological process: negative regulation of Wnt signaling pathway; response to corticosteroid; negative regulation of transcription by RNA polymerase II; positive regulation of transcription by RNA polymerase II; proacrosomal vesicle fusion; regulation of transcription by RNA polymerase II; spermatid development
Cellular component: cytoplasm; cytosol; nucleoplasm; nucleus; chromatin; chromocenter
Genetic constraint (gnomAD): Loss-of-function variants: 17 observed, 51.69 expected, observed/expected ratio (o/e) 0.33, 90% interval 0.22 to 0.49. The upper end of that interval is the gene's LOEUF score, 0.49, which puts it in group 2 of 6, group 1 being the genes least tolerant of losing a copy. Missense variants: 948 observed, 939.27 expected, observed/expected ratio (o/e) 1.01, 90% interval 0.96 to 1.07. Synonymous variants: 421 observed, 383.55 expected, observed/expected ratio (o/e) 1.1, 90% interval 1.01 to 1.19.
Homologues: Orthologues: chimpanzee SOX30 (99% identical), macaque SOX30 (94% identical), pig SOX30 (84% identical), dog SOX30 (83% identical), guinea pig SOX30 (81% identical), rat Sox30 (80% identical), mouse Sox30 (79% identical), tropical clawed frog sox30 (17% identical), Drosophila melanogaster Sox14 (12% identical), Drosophila melanogaster Sox21a (9% identical), Caenorhabditis elegans sox-4 (8% identical). Paralogues in human: SOX6 (15% identical), SOX5 (14% identical), SOX8 (14% identical), SOX9 (14% identical), SOX10 (13% identical), SOX13 (13% identical), CFAP65 (12% identical), SOX7 (11% identical), SOX17 (11% identical), SOX4 (11% identical), SOX18 (10% identical), SOX3 (10% identical), and 8 more.
Diseases named in the same sentence as SOX30 in open-access papers:
SOX30 is named in the same sentence as 28 diseases in open-access papers, as found by Europe PMC text mining. Sharing a sentence is not in itself a finding about the gene and the disease. The quoted sentences say what the papers report.
lung carcinoma (15 papers, 2015 to 2025). "We found that higher mRNA expression of SOX30 was linked to markedly longer OS of lung cancers (HR = 0.76, p = 0.00065)." (PMID 26330328, 2015). "In lung cancers, loss of SOX30 frequently occurs due to its methylation." (PMID 38331879, 2024). "SOX30 deficiency causes tumor metastasis in lung cancer by inducing Wnt signaling overactivation." (PMID 36621836, 2023). "Furthermore, the expression of SOX30 was verified to be closely associated with clinical outcomes in lung cancer patients." (PMID 30002740, 2018). "For example, in lung cancer, SOX30 inhibits cell proliferation, migration, invasion, growth and tumor metastasis." (PMID 38132438, 2023). "Among famously identified SOX transcription factors, SOX containing gene 30 (SOX30) is considered to be a suppressor of a variety of cancers, including hepatocellular carcinoma, lung cancer, ovarian cancer, etc.." (PMID 35836594, 2022). "It has also been proved that the SOX30 gene is frequently silenced or downregulated in lung cancer cell lines and lung cancer samples but expressed in normal human lung tissue." (PMID 33152990, 2020). "Through a methylation-sensitive representational difference analysis, it has been demonstrated that the SOX30 gene promoter is also highly methylated in human lung cancers." (PMID 33152990, 2020). "Patients with a positive SOX30 nuclear expression showed longer overall survival, which indicates that this protein is a key regulator of the metastasis in lung cancer." (PMID 33152990, 2020). "Increased SOX30 expression correlates with long survival time and suggests favorable survival outcomes for lung cancer patients." (PMID 31889959, 2019). "Low SOX30 expression occurs in lung cancer, hepatocellular carcinoma, acute myeloid leukemia, ovarian cancer and bladder cancer." (PMID 31889959, 2019). "Similarly, SOX30 suppresses metastasis of lung cancer and prostate cancer via inhibiting Wnt/β-catenin signaling." (PMID 38331879, 2024). "SOX30 methylation may be a putative epigenetic biomarker for lung cancer, and the knockdown of SOX30 inhibits cell apoptosis and proliferation." (PMID 33152990, 2020). "Thus, the different downstream signal mechanism of SOX30 in these two histological subtypes of lung cancer needs to be further investigated." (PMID 29855376, 2018). "Moreover, SOX30 is silenced by hypermethylation and has been found in lung cancer; SOX30 overexpression inhibits lung cancer cell proliferation, induces cellular apoptosis in vitro, and represses tumor formation in vivo." (PMID 29880037, 2018). "SOX30 as a prognostic biomarker has been reported in lung cancer." (PMID 30002740, 2018). "SOX30 could also inhibited tumor metastasis through attenuating Wnt signaling via the regulation of β-Catenin in a transcriptional and posttranslational manner in lung cancer." (PMID 30002740, 2018). "According to our observation presented above and considering the facts that DSP and JUP can suppress lung cancer progression by inhibition of the Wnt/β-catenin signaling pathway, we hypothesized that SOX30 can suppress the Wnt/β-catenin signaling pathway through upregulation of DSP and JUP." (PMID 29855376, 2018).
lung carcinoma (continued). "To further determine the correction between SOX30 and these genes, we tested for expression of SOX30, DSP, JUP and DSC3 in human lung cancer tissues and adjacent tissues." (PMID 29855376, 2018). "The expression of SOX30, DSP, JUP and DSC3 were detected in lung cancer cell lines, lung tissues of mice and patients’ tissues by qPCR, WB, Immunofluorescence and Immunohistochemistry." (PMID 29855376, 2018). "Although our previous studies have explored the functional role and molecular mechanism of SOX30, its clinicopathological and prognostic significance have not been clarified in lung cancer." (PMID 26330328, 2015). "The role of the SOX proteins, including SOX18 and SOX30, in lung cancer is not very well known." (PMID 33152990, 2020).
lung adenocarcinoma (7 papers, 2015 to 2025). A carcinoma that arises from the lung and is characterized by the presence of malignant glandular epithelial cells. "The prognostic role of SOX30 expression has only been studied in lung adenocarcinomas, where a low expression of this factor in the stromal tumor was associated with a worse prognosis for patients." (PMID 33152990, 2020). "In order to clarify this further, the effect of SOX30 on cell proliferation and apoptosis was examined in lung adenocarcinoma and squamous-cell carcinoma cell lines by using the gain-of-function mice model." (PMID 33152990, 2020). "Overall, these findings demonstrate for the first time that SOX30 acts as a master switch of desmosomal genes, inhibits lung adenocarcinoma cell proliferation, migration and invasion by activating the transcription of desmosomal genes." (PMID 29855376, 2018). "In human lung adenocarcinomas, SOX30 expression correlates well with the histological type as well as lymphatic metastasis; high SOX30 expression is related to favorable survival." (PMID 29880037, 2018). "a Heatmaps for correlations between SOX30 and PKP3 in the TCGA lung adenocarcinoma RNAseq (IlluminaHiSeq; n = 571) and TCGA lung squamous carcinoma RNAseq (IlluminaHiSeq; n = 553) data set." (PMID 29855376, 2018). "The role of the SOX18 and SOX30 expression in non-small-cell lung cancers (NSCLCs), especially in lung adenocarcinoma (AC) and lung squamous-cell carcinoma (LSCC), is not yet fully understood." (PMID 33152990, 2020). "The expression of desmosomal genes were upregulated by SOX30 in lung adenocarcinoma but not in lung squamous carcinoma." (PMID 29855376, 2018). "Further mechanism studies showed that SOX30 acts as a key transcriptional regulator of desmosomal genes by directly binding to the ACAAT motif of desmosomal genes promoter region and activating their transcription in lung adenocarcinoma." (PMID 29855376, 2018). "In particular, SOX30 is a favorable and independent prognostic factor in one main subtype of NSCLC, lung adenocarcinoma (ADC) patients (n = 150, P = 0.000, HR = 0.405), but not in another main subtype of NSCLC, squamous cell carcinoma patients." (PMID 26330328, 2015).
bladder cancer (6 papers, 2018 to 2023). "For instance, previous research has presented that a positive association is found between SOX30 expression and OS in bladder cancer patients." (PMID 35836594, 2022). "The overexpression of SOX30 in bladder cancer cell lines (T24 and 5637) results in the inhibition of cell proliferation and invasion and promotion of apoptosis mechanisms." (PMID 33152990, 2020). "SOX30 mRNA expression was quantified in bladder cancer tissue, paired adjacent normal tissue, and cell lines with qRT-PCR." (PMID 29880037, 2018). "Overexpression of SOX30 inhibits the proliferation, invasion, and migration of bladder cancer." (PMID 36575440, 2022). "Similarly to prostate cancer, SOX30 expression shows a lower expression in bladder cancer (BC) compared to adjacent normal tissue." (PMID 33152990, 2020). "Notably, decreased SOX30 expression occurs in hepatocellular carcinoma, acute myeloid leukemia, malignant lymphomas, ovarian cancer and bladder cancer." (PMID 31889959, 2019). "Moreover, low SOX30 expression correlated with reduced survival rates and its overexpression impaired cell proliferation, invasion and migration, and at the same time, it elevated the apoptosis of bladder cancer cells." (PMID 38132438, 2023). "Therefore, the overexpression of SOX30 in BC cells could inhibit the progression and development of bladder cancer." (PMID 33152990, 2020).
Azoospermia (5 papers, 2017 to 2025). Absence of any measurable level of sperm,whereby spermatozoa cannot be observed even after centrifugation of the semen pellet. "In summary, Sox30 primarily drives the development and differentiation spermatocytes, and loss of Sox30 results in spermatocytes arrested at meiosis I, which is probably the rationale cause of azoospermia." (PMID 39971903, 2025). "Our previous results have indicated that silencing SOX30 is possibly a crucial contributor to azoospermia disease." (PMID 33721419, 2021). "Our latest study has revealed that epigenetic silencing of SOX30 is a key contributor to male infertility and may offer a therapeutic target for azoospermia in humans." (PMID 33721419, 2021). "However, the precise pathogenesis and mechanism of azoospermia induced by SOX30 silencing remain unclear." (PMID 33721419, 2021). "Our results suggest that SOX30 mutations may underlie some instances of unexplained non-obstructive azoospermia in humans." (PMID 29247201, 2017). "Importantly, transcriptome co-expression analysis in non-obstructive azoospermia (NOA) testes identifies SOX30 as a central regulator of NOA transcriptional networks." (PMID 41467312, 2025).
male infertility (5 papers, 2017 to 2025). The inability of the male to effect fertilization of an ovum after a specified period of unprotected intercourse. "The revelation of Sox30 properties in male testis provides enticing possibilities of its role in fine meiotic process and far-ranging spermatogenesis, testicular cell homeostasis regulation and additional male infertility." (PMID 39971903, 2025). "SOX30 variants have been associated with male infertility with testis-specific expression and have never been associated with neurological traits." (PMID 36672963, 2023).
prostate carcinoma (5 papers, 2019 to 2025). A carcinoma that arises from epithelial cells of the prostate gland. "Since SOX30 expression decreased in prostate cancer, we explored the underlying mechanism responsible for this reduction." (PMID 31889959, 2019). "Here, the inhibitory effect of SOX30 overexpression or miR-653-5p inhibition on prostate cancer cell proliferation and invasion was associated with a suppressive effect on the activation of Wnt/β-catenin signaling." (PMID 31889959, 2019). "SOX30 upregulation due to miR-653-5p inhibition restricted the proliferation and invasion of prostate cancer cells, and this was associated with Wnt/β-catenin signaling suppression." (PMID 31889959, 2019). "We also identified that the miR-653-5p oncogenic effect in prostate cancer is associated with its inhibitory effect on SOX30." (PMID 31889959, 2019). "Moreover, it was discovered that a lower SOX30 expression in Prostate Cancer (PC) cells compared to normal tissue cells is caused by the inhibiting effect of miR-653-5p’s interaction with the SOX30 transcript, which results in the downregulation of Wnt/β-catenin signaling." (PMID 33152990, 2020). "MiR-183-5p downregulates MUC15, inducing SOX2 expression via the c-MET/PI3K/AKT axis, while miR-653-5p upregulates SOX30 in prostate cancer." (PMID 38331879, 2024). "In prostate cancer, SOX30 acts as a tumor suppressor, similarly to what happens in other types of cancer." (PMID 33152990, 2020). "We found that SOX30 expression was lower in prostate cancer cells than in normal tissues and that it is a miR-653-5p target gene." (PMID 31889959, 2019). "SOX30 expression was lower in cells of prostate cancer lines than in cells of the normal prostate epithelial line." (PMID 31889959, 2019). "SOX30 gain-of-function experiments gave more insight into its biological function in prostate cancer." (PMID 31889959, 2019). "SOX30 overexpression or miR-653-5p inhibition markedly repressed the proliferation and invasion of prostate cancer cells through downregulation of Wnt/β-catenin signaling." (PMID 31889959, 2019). "In this study, we found decreased SOX30 expression in prostate cancer tissues and cell lines and showed that its overexpression significantly represses the proliferation and invasion of prostate cancer cells." (PMID 31889959, 2019). "SOX30 was identified as a target gene of microRNA-653-5p (miR-653-5p), which is upregulated in prostate cancer tissues." (PMID 31889959, 2019). "Our results reveal a tumor-suppressive function for SOX30 in prostate cancer and highlight the importance of the miR-653-5p–SOX30–Wnt/β-catenin signaling axis in prostate cancer progression." (PMID 31889959, 2019). "Overall, these results suggest that miR-653-5p inhibition exerts an anti-tumor effect in prostate cancer cells by upregulating SOX30." (PMID 31889959, 2019). "SOX30 protein expression was also consistently lower in prostate cancer cell lines compared with normal prostate epithelial cells." (PMID 31889959, 2019). "Quantitative real-time PCR analysis showed that SOX30 mRNA expression was significantly lower in prostate cancer cell lines than in normal prostate epithelial cell lines." (PMID 31889959, 2019). "The findings of our study demonstrate that SOX30 is a tumor-suppressive gene in prostate cancer and an miR-653-5p target." (PMID 31889959, 2019). "Further investigation is needed to elaborate on the regulation of SOX30 by miRNAs in prostate cancer." (PMID 31889959, 2019). "We next investigated the molecular basis for SOX30 regulation of prostate cancer cell proliferation and invasion." (PMID 31889959, 2019). "Our findings highlight the involvement of the miR-653-5p–SOX30–Wnt/β-catenin signaling axis in prostate cancer progression." (PMID 31889959, 2019). "As expected, SOX30 silencing significantly reversed the inhibitory effect of miR-653-5p inhibition on prostate cancer cell proliferation and invasion." (PMID 31889959, 2019).